GJB2 (gap junction protein beta 2)
Diseases named in the same sentence as GJB2 in open-access papers (continued):
Sharing a sentence is not in itself a finding about the gene and the disease.
hearing loss (continued). "Of the 80 children with congenital bilateral hearing loss in the study, 59 (74%) were found to have genetic variants that may cause congenital deafness, including 44 with GJB2 or SLC26A4 gene variant, 1 with STRC gene variant, and 14 with other genetic variants that may cause deafness." (PMID 36142981, 2022). "Dominant variants in the gap junction beta-2 (GJB2) gene may lead to various degrees of syndromic hearing loss (SHL) which is manifest as sensorineural hearing impairment and hyperproliferative epidermal disorders, including palmoplantar keratoderma with deafness (PPKDFN)." (PMID 35938034, 2022). "There are great variations in the allele frequency of patients with GJB2 mutations in each population, suggesting that the allele frequency in the population, which reflects a founder effect, strongly affects the status of the GJB2 gene in the hearing loss population." (PMID 34599366, 2022). "Although the distribution of hearing loss-associated mutations seemed to be distinct between various ethnic groups (such as mutations on GJB2), the disparate number of populations of different ethnic groups might hamper the statistical comparison between majorities with minorities." (PMID 34917556, 2021). "Therefore we may observe ethnic-specific variants like the c.71G>A (p.W24*) in the GJB2 gene, which is responsible for a substantial number of hearing loss cases in the Roma population, and in Indian cases as well." (PMID 32847582, 2020). "Notably, GJB2 mutations are found in patients with nonsyndromic hearing loss." (PMID 33147893, 2020). "Since a large number of GJB2 mutation patients have late onset of hearing loss, pinpointing the molecular mechanism of the mutation could help formulate strategies to prevent or delay hearing loss in this specific patient population and develop potential treatments." (PMID 31562289, 2019). "Because the p.V37I variant has been reported to be associated with delayed onset of hearing impairment, Li indicated that the p.V37I exclusive genotype of GJB2 might cause subclinical hearing impairment at birth and increase the risk for postnatal permanent childhood hearing impairment." (PMID 26061099, 2015). "The distribution of homozygous p.V37I variation or compound p.V37I plus other GJB2 pathogenic mutation (2.75%) in the patient groups was significantly higher than that in the control group (0%), suggesting that the presence of p.V37I variation was more frequently associated with hearing loss." (PMID 26061099, 2015). "The allele frequency of p.R127H, classified as a pathogenic GJB2 mutation, was significantly higher in the patient group than in the control group (P<0.05), indicating that p.R127H may be a mutation in the Chinese Tibetan hearing loss population." (PMID 22389666, 2012). "A total of 199 (19.6%) babies were found to have at least 1 mutated allele on the NGS for deafness, 11 (1.1%) of whom were homozygous for GJB2 p.V37I, 6 (0.6%) compound heterozygous for GJB2 p.V37I and c.235delC, and 1 (0.1%) homoplasmic for m.1555A>G, who may potentially have hearing loss." (PMID 21811586, 2011). "Therefore, GJB2 is normally the first gene to be tested in patients with hearing loss." (PMID 21122151, 2010). "Amongst other genetic variants, Gjb2 and Gjb6, which encode connexin 26 (Cx26) and connexin 30 (Cx30), respectively, are responsible for DFNB1, the principal cause of non-syndromic hearing loss in the Mediterranean population." (PMID 41601591, 2026). "In three previous studies, we detected the GJB2 (MIM 121011) and LRTOMT (MIM 611451) variants and CDC14A (MIM608653) variants implicated in hearing impairment in the Mauritanian population." (PMID 39230647, 2025). "Testing for the GJB2 gene is commonly carried out as a primary screening test for any hearing impairment." (PMID 39230647, 2025).
hearing loss (continued). "We explored a possible genotype–phenotype correlation in our cohort, excluding patients with pathogenic biallelic c.35delG GJB2 variants and POU3F4 variants, which are known to lead to severe hearing loss phenotypes." (PMID 40121402, 2025). "While the link between GJB2 or GJB6 variants and hearing loss is well-established, the exact role of inner ear connexins in the development of deafness remains incompletely understood." (PMID 41463117, 2025). "In the present study, 57% of 35 children with GJB2 and SLC26A4 hearing loss were identified by newborn hearing screening with audiometric testing alone." (PMID 40008839, 2025). "Although more than 277 pathogenic and likely pathogenic variants in the GJB2 gene have been described, only nine large deletions at the DFNB1 locus have been shown to contribute to hearing loss." (PMID 40981390, 2025). "Gene therapy trials are ongoing for congenital forms of hearing loss caused by single-gene mutations (e.g., OTOF, GJB2), with early results suggesting partial restoration of auditory function." (PMID 41463124, 2025). "The genetic variants of GJB2, SLC26A4, LMX1A are involved in inner ear development and associated with the occurrence of asymmetric sensorineural hearing loss." (PMID 39373914, 2025). "Patients with genetic variants of GJB2, SLC26A4, and LMX1A showed significantly higher detection of EH compared to other causes of hearing loss." (PMID 39373914, 2025). "The combination of genetic and physiologic hearing screening in newborns had the potential to increase identification rates from 57% to 66% in a cohort of children with GJB2 and SLC26A4 hearing loss." (PMID 40008839, 2025). "Here, we comprehensively reviewed the clinical characteristics of GJB2 and SLC26A4-related hearing loss, in addition to the physiological functions and pathogenesis of HL caused by mutations in these genes." (PMID 39609929, 2024). "Mutations in GJB2 (gap junction beta 2, encoding gap junction protein 26 [Connexin26, CX26]) cause severe human non‐syndromic sensorineural hearing loss." (PMID 39188517, 2024). "For hearing loss, mutations in the GJB2 gene encoding Cx26, one of 21 distinct Cx genes in humans, account for as much as 50% of severe-to-profound inherited deafness cases across diverse ethnic populations." (PMID 39302316, 2024). "Other studies also indicated that, apart from GJB2, pathogenic variants in SLC26A4, MYO15A, OTOF, and CDH23 are a frequent cause of hearing loss in European populations (Hilgert, Smith, Van Camp, 2009)." (PMID 39498320, 2024). "However, recent studies have shown that K+ circulation is rarely associated with the pathological process of GJB2-related hearing loss, while cochlear developmental disorders and oxidative stress play an important, even critical, role in the occurrence of GJB2-related hearing loss." (PMID 37333892, 2023). "To identify the genetic cause of hearing loss, we performed WES in 373 families with hearing loss after prescreening for GJB2 and SLC26A4, the two most commonly mutated genes associated with hearing loss in Koreans." (PMID 37009795, 2023). "It has been suggested that several mutations such as c.235delC in GJB2, A194T in GJB3, 150‐kb large deletion in GJB6 are the important causes for non‐syndromic hearing loss in many populations worldwide." (PMID 34811812, 2022). "Molecular epidemiological studies in China have identified several common deafness genes, such as GJB2, SLC26A4, and MT-RNR1, which account for 30%–50% of congenital hearing loss cases." (PMID 36568381, 2022). "Presence of the two distinct Mendelian forms, i.e., β-sarcoglycanopathy and GJB2-related hearing impairment, in a same patient highlights the significance of genetic counseling in patients with β-sarcoglycanopathy." (PMID 35813381, 2022). "Non-syndromic hearing loss (i.e., DFNB1) is mostly due to GJB2 (Gap Junction Beta 2) variations and DFNB1 large deletions." (PMID 35805969, 2022).
hearing loss (continued). "For instance, GJB2 (one UF) and MARVELD2 (one UF) cause early-onset hearing loss, which itself cannot be prevented, but morbidity associated with the hearing loss, such as speech and language delay, can be mitigated at a young age." (PMID 34697415, 2022). "Within the over 20 pathogenic variants reported leading to ARNSHL, it is especially the large deletions in the GJB2 or GJB6 genes that lead to hearing impairment either in a homozygous, heterozygous or compound heterozygous state." (PMID 36672810, 2022). "This study aimed to investigate GJB2 (MIM: 121011) and GJB6 (MIM: 604418) variants associated with familial non-syndromic hearing impairment (HI) in Senegal." (PMID 35625523, 2022). "We also identified variants and genes that cause recessive hearing loss (GJB2 Gly12fs and SLC26A5 pLOF+strict deleterious missense mutations), associated with increased risk (OR~1.2–1.3) for hearing loss in heterozygous carriers." (PMID 35661827, 2022). "Connexins have received considerable attention in the field of hereditary hearing loss because up to 50% of cases of congenital, autosomal-recessive, non-syndromic deafness can be attributed to variants in the gene GJB2, which encodes connexin 26 (CX26)." (PMID 34356098, 2021). "Different pathogenic mutations in the GJB2 gene can affect all stages of the Cx26 life cycle and result in nonsyndromic autosomal recessive (DFNB1) or dominant (DFNA3) deafness and syndromes associating hearing loss with skin disorders." (PMID 33466560, 2021). "Mutations in connexin genes—Cx26 (GJB2), Cx30 (GJB6), Cx29 (GJC3), Cx31 (GJB3) and Cx43 (GJA1)—have been identified as the culprits for hearing loss with distinct pathological changes in the cochlea." (PMID 33917368, 2021). "Clinically, except for late-onset hearing impairment, some GJB2 c.235delC homozygous patients show post-lingual and/or mild to moderate hearing impairment instead of profound hearing loss with a highly heterogeneous phenotype." (PMID 33718389, 2021). "Nevertheless, in most African populations, GJB2 and GJB6 variants are rarely implicated in hearing impairment with some GJB2 cases found in Morocco, Sudan, and Kenya, yet an exceptionally high prevalence is found in Ghana." (PMID 32012697, 2020). "GJB2 or GJB6, encoding for connexin 26 and 30, respectively, are two major deafness genes that induce a high incidence of non-syndromic hearing loss, both autosomal dominant (DFNA3) as recessive (DFNB1)." (PMID 33193034, 2020). "Almost 60% of children with profound prelingual hearing loss (HL) have a genetic determinant of deafness, most frequently two DFNB1 locus (GJB2/GJB6 genes) recessive pathogenic variants." (PMID 31952308, 2020). "GJB2 (NM_004004.5) or Gap Junction Protein β 2, situated on chromosome 13q12 (DFNB1 locus), is the most common cause of congenital hearing loss in many populations including European and Mediterranean countries." (PMID 33333757, 2020). "GJB2, which codes a gap junction protein, connexin 26 (Cx26), was the first gene identified as being involved with non‐syndromic hearing impairment." (PMID 32027099, 2020). "Genetic variants in GJB2 and GJB6 genes are the most frequent causes of hereditary hearing loss among several deaf populations worldwide." (PMID 33096615, 2020). "Molecular epidemiological studies have found several common deafness genes, such as GJB2, SLC26A4, and mitochondrial 12S rRNA, which appear to account for 30–50% of congenital hearing loss cases." (PMID 31541171, 2020). "Mutations in three genes encoding connexin, GJB2 (Cx 26), GJB6 (Cx 30), and GJB3 (Cx 31), were found to cause hearing impairment, and the occurrence in the first two are most frequently described." (PMID 30837189, 2020). "We performed a genetic screening of GJB2 gene (responsible for the major etiologies of hereditary hearing impairment among Romanians), GJB3, GJB6, POU3F4 and WFS1 genes." (PMID 33333757, 2020).
hearing loss (continued). "Sanger sequencing was applied to analysis of coding (exon 2) and non-coding regions of GJB2 in a cohort of Tuvinian patients with hearing impairments (n = 220) and ethnically matched controls (n = 157)." (PMID 31195736, 2019). "Consistent with previous publications, GJB2 and SLC26A4 were the major genetic causes of hearing loss in the Chinese population; the main contributing variants were GJB2 c.235delC, GJB2 c.109G > A, and SLC26A4 c.919-2A > G." (PMID 31138263, 2019). "This study aimed to investigate GJB2 (connexin 26) and GJB6 (connexin 30) mutations associated with familial non-syndromic childhood hearing impairment (HI) in Cameroon." (PMID 31731535, 2019). "In our study, we have investigated the frequency of three common deafness‐related genes, GJB2, SLC26A4, and mtDNA 12S rRNA, in the patients with non‐syndromic hearing loss from Shanxi Province, an area with a high birth defect rate." (PMID 30693673, 2019). "The low implication of the GJB2 gene in non-syndromic hearing impairment has also been demonstrated in other populations of African descent." (PMID 31731535, 2019). "This study aimed to discuss the GJB2 gene status in an Iranian population with hearing impairment who referred for prenatal testing." (PMID 30989077, 2019). "The most common non-syndromic genetic causes of deafness are Cx26 mutations (GJB2); they are manifested as congenital uni- or bilateral hearing loss/deafness, which can also be progressive." (PMID 31998167, 2019). "DFNB1, the first locus to have been associated with deafness, has two major genes GJB2 & GJB6, whose mutations have played vital role in hearing impairment across many ethnicities in the world." (PMID 29921236, 2018). "It has been found that mutations in the Connexin26 (Cx26, GJB2) gap junctional gene induce a high incidence of hearing loss, accounting for more than 50% of the cases of nonsyndromic hearing loss." (PMID 29710868, 2018). "In particular, GJB2, SLC26A4, MYO15A, OTOF, and CDH23 are the most common genes responsible for hereditary hearing loss." (PMID 30068307, 2018). "After mutations in the GJB2 and GJB6 genes, mutations in SLC26A4 are considered the major cause of hereditary hearing loss in the Brazilian population and in many other populations, contributing to up to 14% of cases of moderate, profound or severe deafness." (PMID 30068397, 2018). "The GJB2, SLC26A4, MT-RNR1 and MT-TS1 genes have been reported as major pathogenic genes in nonsyndromic hearing loss." (PMID 28225033, 2017). "We developed a PCR-reverse dot blot (RDB) assay for screening 20 hotspot mutations of GJB2, GJB3, SLC26A4, and MT-RNR1, which are common non-syndromic hearing loss (NSHL)–associated genes in the Chinese population." (PMID 28505178, 2017). "Genetic analysis of 115 variants in common genes related to HL, GJB2, SLC26A4 and MT-RNR, was performed on 695 subjects with non-syndromic hearing loss (NSHL) from the Northern China." (PMID 27792752, 2016). "In thisstudy, we analyze nine common gene mutations (GJB2,SLC26A4, GJB3 and MT-RNR1) in 738children with severe or profound hearing loss in Inner Mongolia." (PMID 27727359, 2016). "The GJB2 gene is the most commonly implicated gene in hereditary hearing loss and has been associated with both autosomal recessive (DFNB1A (OMIM #220290)) and autosomal dominant (DFNA3A (OMIM #601544)) hearing impairment." (PMID 27761313, 2016). "In contrast to the positive results seen in the Gjb2-CKO mice, the ACEMg diet had a detrimental effect on mice with AUNA1 hearing loss." (PMID 26965868, 2016). "The complete resequencing of promoter and coding region of the GJB2 gene was performed for the first time in 580 persons in Yakutia, of which 393 patients were having congenital hearing impairment (360 unrelated) and 187 were normal hearing individuals." (PMID 27829488, 2016).
hearing loss (continued). "For example, while variants in GJB2 were the most common cause of severe-to-profound hearing loss (20 %), STRC accounted for 30 % of diagnoses in persons with mild-to-moderate hearing loss, followed closely by GJB2 (25 %) and then TECTA (7 %)." (PMID 26969326, 2016). "The DFNB1 locus, which contains the GJB2 and GJB6 genes, plays a key role in nonsyndromic hearing loss." (PMID 26075227, 2015). "Mutations in the Gap junction β2 gene (GJB2) (OMIM 121011; DFNB1), which encodes connexin 26, are responsible for nearly half of the cases of hearing loss in many populations." (PMID 26061264, 2015). "The current study evaluated the relationships between polymorphisms in the GJB2 and GJB6 genes and autosomal recessive nonsyndromic hearing loss in a sample of the Brazilian population." (PMID 26075227, 2015). "In this study, we present the data on age-related hearing impairment of 48 heterozygous carriers of mutation IVS1+1G>A (GJB2 gene) and 97 subjects with GJB2 genotype wt/wt in the Republic of Sakha/Yakutia (Eastern Siberia, Russia)." (PMID 24959830, 2014). "The GJB2, MT-RNR1, and SLC26A4 genes have been reported as common causative genes of hearing loss in the Korean population and some mutations of these genes are the most common mutations associated with hearing loss." (PMID 23469187, 2013). "Our findings provide a basis for future studies to determine the impact of mutations of the GJB2 and SLC26A4 genes and congenital CMV infection on speech and language outcomes in children with hearing loss." (PMID 23555729, 2013). "In Japanese, GJB2, SLC26A4, CDH23 and the 1555A>G mutation in the mitochondrial 12S rRNA are the major causes of hearing loss." (PMID 24053799, 2013). "They showed that p.V37I exclusive genotype of GJB2 was present in 20% of postnatal permanent childhood hearing impairment subjects." (PMID 23637863, 2013). "Approximately 50% of autosomal recessive nonsyndromic hearing loss can be attributed to the disorder DFNB1, caused by mutations in GJB2 (which encodes the protein connexin 26) and GJB6 (which encodes the protein connexin 30)." (PMID 23648117, 2013). "We also considered the mutations in the GJB2, GJB6 and SLC26A4 genes which are recognised to be among the most frequent causes of hearing impairment." (PMID 23969527, 2013). "Several forms of hearing loss have been imputated to connexins mutations and prevalently to connexin 26 (Cx26) codified by the GJB2 gene (gap junction protein, beta 2)." (PMID 22547955, 2011). "The important role of intercellular communication, particularly that between GJB2 and GJB6 (encoding CX26 and CX30), has been confirmed by evidence that certain connexin gene mutations cause sensorineural hearing loss." (PMID 21731760, 2011). "After the systematic comparison of various genes in different countries or ethnic differences between the mutation frequencies, we calculated the average frequency of GJB2, GJB3, GJB6, SLC26A4 and mtDNA mutations in patients with nonsyndromic hearing loss." (PMID 23554706, 2011). "Dysfunctional gap junctions caused by GJB2 (CX26) and GJB6 (CX30) mutations are implicated in nearly half of nonsyndromic hearing loss cases." (PMID 21731760, 2011). "In this study, we screened the GJB2, GJB3, GJB6, SLC26A4, SLC26A5 IVS2-2A>G and mitochondrial genes to determine the etiology of hearing loss in eastern China." (PMID 23554706, 2011). "For auditory function, the important role of intercellular communication via gap junctions has been confirmed by findings that certain CX gene mutations, particularly those of GJB2 and GJB6, cause hearing loss." (PMID 21731760, 2011). "Mutations in three connexin encoding genes, GJB2 (Cx 26), GJB6 (Cx 30), and GJB3 (Cx 31) have been found to cause hearing loss." (PMID 20835527, 2010). "It was employed for multiplex detection of 11 mutations in GJB2, GJB3, SLC26A4 and mitochondrial DNA causing hereditary hearing loss." (PMID 19366456, 2009).